IL18 (interleukin 18)
Diseases named in the same sentence as IL18 in open-access papers (continued):
Sharing a sentence is not in itself a finding about the gene and the disease.
Obesity (continued). "In the opposite direction, NLRP1 inflammasome was described to prevent obesity and metabolic syndrome through IL18 production." (PMID 32012784, 2020). "In direct contrast, IL-18 and IL-33 have been demonstrated to play a protective role in animal models of obesity-driven metabolic syndrome, although the precise mechanisms through which this occurs have not been identified." (PMID 31488830, 2019). "Caspase 1 knockout mice kept under HFD has been shown to develop obesity due to reduced IL-18 levels." (PMID 31998283, 2019). "On the other hand, in mice with inhibited IL-18 synthesis or with deficiency of inflammasome NLPR1, which is responsible for IL-18 synthesis, obesity, insulin resistance and other metabolic syndrome symptoms were observed." (PMID 31771099, 2019). "Recently it was shown that the Nlrp1 inflammasome, through the maturation of IL-18 in the adipose tissue, regulates the development of obesity and metabolic syndrome resulting from a rich caloric diet in C57BL/6 mice, by promoting lipolysis." (PMID 31554824, 2019). "Male sex, obesity, diabetes, and plasma levels of cystatin C, GDF‐15, and CRP‐hs were independently associated with higher IL‐18 levels." (PMID 31596518, 2019). "On the one hand, in people with diabetes, metabolic syndrome, or obesity the IL-18 level is significantly higher than in healthy people." (PMID 31771099, 2019). "Given that both the NLRP3 and NLRP1 inflammasome produce mature caspase-1 to cleave IL-18 and IL-1β, how these opposing effects occur, and in which cellular compartments, to drive or limit obesity remain unanswered questions that will be important to resolve." (PMID 29515457, 2018). "Conversely, skeletal muscle IL18-overexpression induces resistance to dietary obesity in mice through induction of AMPK signalling and lipid oxidation, which can then balance lipid accumulation on a HFD." (PMID 30158466, 2018). "In adipose tissue, NLRP1 is an innate immune sensor that functions in the context of metabolic stress to produce IL-18, preventing obesity and diet-induced metabolic dysfunction." (PMID 29342149, 2018). "In vivo, while the amount of food and energy intake of Il18−/− mice was higher compared with the controls, resulting in obesity, insulin resistance and diabetes mellitus, the metabolic rate of Il18−/− mice was similar to that of the controls." (PMID 30453990, 2018). "Obesity promotes macrophage recruitment and the secretion of numerous inflammation cytokines as TNFβ, IL-1, IL-6, and IL-18." (PMID 30390093, 2018). "Taken together, in the progression toward obesity, there is continual production of IL-18 to oppose ectopic lipid accumulation." (PMID 29342149, 2018). "Despite displaying greater obesity, IL-18 knockout mice fed with WD for 8 weeks had preserved cardiac diastolic function and higher left ventricular ejection fraction." (PMID 28394363, 2017). "The observation that IL-18 KO mice are obese yet have better cardiac function than the leaner WT mice is vaguely reminiscent of the 'obesity paradox' in patients with HF, by which patients with HF and are obese tend to have a more favorable prognosis." (PMID 28394363, 2017). "Our data represent the IL‐18R/IL‐18 axis changes with regard to obesity/T2D that are globally expressed at the gene and protein levels in the adipose tissue." (PMID 28508444, 2017). "Moreover, direct participation of NLRP3 in obesity has been confirmed in studies that have shown that in gene-deficient mice fed with a high-fat diet, activation of caspase-1 and expression of pro-IL-1b in adipose tissue, and serum loss of IL-18 compared to the wild-type phenotype is reduced." (PMID 28319103, 2017). "IL-18 levels are elevated in AD brains, as well as in diseases that increase AD risk, including T2DM, obesity, and ischemic heart disease." (PMID 28531131, 2017).
Obesity (continued). "IL-18 KO mice had better cardiac function despite greater weight gain, showing that in response to WD, obesity and cardiac dysfunction occur simultaneously, yet the former is not the cause for the latter." (PMID 28394363, 2017). "In conclusion, our data show that IL‐18R/IL‐18 mRNA and protein expression was elevated (although mainly on immune cells) in the adipose tissue in obesity." (PMID 28508444, 2017). "Our data showing enhanced IL‐18R/IL‐18 global expression in the adipose tissues of diabetic/non‐diabetic obese and overweight as compared with lean subjects point to obesity as a positive modulator of the IL‐18R/IL‐18 axis in this compartment." (PMID 28508444, 2017). "Taken together, we show that HFD-induced obesity is accompanied by an increase of ceramides, activation of inflammasome in AT, and a secretion of several proinflammatory cytokines including IL-18 that all are known to affect glucose sensitivity." (PMID 26788518, 2016). "IL-18, a member of the IL-1 family, is increased in the presence of obesity, diabetes, and the polycystic ovary syndrome (PCOS)." (PMID 27747236, 2016). "Activation of the NLRP-3 inflammasome in course of diet-induced obesity in mice led to an increase in IL-18 secretion and was shown to affect insulin signaling." (PMID 26788518, 2016). "While IL-18 is secreted primarily by macrophages and other immune cells, adipocytes are capable of constitutively producing IL-18 and increase IL-18 synthesis in obesity." (PMID 27067270, 2016). "The proinflammatory cytokines TNF-α and IL-18 are known to be elevated in obesity/T2D while IL-8 or CXC chemokine ligand (CXCL)-8 is an inflammatory protein and increased circulatory numbers of IL8-expressing monocytes were also reported in human obesity." (PMID 27980459, 2016). "IL-18 is a pro-inflammatory cytokine expressed in macrophages but also adipocytes and muscle cells and its expression correlates with obesity, type 2 diabetes and the metabolic syndrome." (PMID 27902747, 2016). "Our data showing increased TNF-α, IL-18, and IL-8 expression in obesity are in agreement with studies showing induction of these proinflammatory proteins in obese humans." (PMID 27980459, 2016). "The effect of follicular fluid and serum IL-18 levels on the outcome of pregnancy, obesity, and the number of acquired oocytes was also analyzed." (PMID 27747236, 2016). "A recent literature showed that the activation of NLRP1 inflammasome and subsequent IL-18 production prevent obesity and metabolic syndrome, indicating that NLRP1/IL-18 axis prevents T2D and likely DN." (PMID 27706238, 2016). "The most significant alterations of immune markers associated with HFD-induced obesity in serum were those of TNF-α, IL-18 and IL-17A, whose concentrations significantly increased (p<0.001–0.013)." (PMID 26161548, 2015). "Feed efficiency differences depending on the dietary fat amount suggested that Il18r1-KO were less obesity-prone than Il18-null mice, through either divergence in substrate utilization and/or energy expenditure." (PMID 26656097, 2015). "Circulating levels of IL-18 are elevated in obesity and correlate with body mass index, adiposity and insulin resistance." (PMID 23675517, 2013). "After stepwise multiple linear regression analysis both OPN and IL-18 were found to be independently associated with BMI (P<0.05) which indicated that obesity contributed to the upregulation of OPN and IL-18 levels in plasma and in PBMCs." (PMID 23675517, 2013). "We argue that IL-18 levels are elevated during obesity-induced inflammation, a condition which favors upregulation of the OPN in circulation and adipose tissue." (PMID 23675517, 2013). "Previously it has been shown in different studies that high expression of OPN and IL-18 correlated with obesity-induced inflammation and insulin resistance." (PMID 23675517, 2013).
Obesity (continued). "In the IL-12+ IL-18 model, both diet-induced and genetic obesity significantly increase AP severity and delay resolution through mechanisms that include altered inflammatory responses and induction of fat necrosis." (PMID 22815875, 2012). "IL18 is proinflammatory and levels are elevated in obesity and type 2 diabetes and are correlated with traits of the metabolic syndrome." (PMID 22474579, 2012). "IL-1ra and IL-18 correlated with all anthropometrical measurements of obesity, including body weight, BMI, BMI-SDS, and waist circumference, whereas IL-1α did not." (PMID 20169140, 2010). "In our adolescent cohort, IL-18 is elevated in overweight individuals and correlates with different anthropometrical measurements of obesity." (PMID 20169140, 2010). "Both proinflammatory cytokines, IL-1β and IL18, are elevated in adult obesity and share a similar signal transduction pathway." (PMID 20169140, 2010). "Work on IL-18 null, and on IL-18BP overexpressing mice indicated that IL-18 is anorexigenic and can modulate feeding, but also energy homeostasis, influencing obesity and insulin resistance." (PMID 20113500, 2010). "On the other hand, IL‐18 cytokine may control adipose tissue expansion since its absence determines spontaneous obesity in mice." (PMID 41508774, 2026). "In addition, patients with elevated pre-RT IL-18 levels and obesity experienced the highest odds of post-RT pain (OR = 3.97, 95% CI: 1.98-7.98) and RT-related pain (OR = 2.84, 95% CI: 1.32-6.09), suggesting a potential combined effect." (PMID 41976322, 2026). "The joint effect of IL-18 and obesity on pain were also explored." (PMID 41976322, 2026). "We also analyzed the IL‐18 expression in oWAT and sWAT from patients with severe obesity." (PMID 41508774, 2026). "Obesity exacerbates inflammation through immune cell activation in adipose tissue and the release of proinflammatory adipokines, such as leptin, resistin, and IL-18, which enhance autoimmune responses and insulin resistance." (PMID 40277935, 2025). "Moreover, elevated levels of TNF-α stimulate the generation of collagen and extracellular matrix protein, and IL-18 is a key mediator linking obesity to systemic inflammation and nephropathy." (PMID 40703753, 2025). "However, in obesity and insulin resistance, IL-18 appears to counteract cardiometabolic dysfunction via the NLRP1 inflammasome." (PMID 39940942, 2025). "This could be due to the favorable role of NLRP1 on IL-18 production, as IL-18 deletion has been found to link to obesity and insulin resistance." (PMID 40433411, 2025). "Statistically, the concentrations of GROα, IL-2, IL-4, IL-6, IL-17A, IL-22, IL-23, and MCP-3 were significantly higher in males with obesity compared to the females with obesity, while the concentrations of IL-5, IL-10, IL-18, MCP-1, and MIP2α trended higher (p ≤ 0.1)." (PMID 41488663, 2025). "Elevated levels of IL-18 and its receptor were reported in women with PCOS, correlating with IR, obesity, and hyperandrogenism and it is implicated in the inflammatory processes that contribute to metabolic syndrome, a condition associated with an increased risk of cardiovascular events." (PMID 39858399, 2024). "Adipokines such as leptin and proinflammatory cytokines such as TNFα, IL-6 and IL-18 are involved in the pathogenesis of obesity-related insulin resistance in women with PCOS but seem also to be directly implicated in the pathogenesis of ovarian and adrenal dysfunction." (PMID 38540265, 2024). "In children with obesity, monitoring IL-18 could help in predicting fatty livers and advanced liver steatosis." (PMID 39275140, 2024). "Interestingly, mice models with IL-18 knockout developed obesity independently of the type of diet (high-fat or low-fat)." (PMID 39275140, 2024). "Taking into account previously published studies about the inhibiting role of IL-18 in appetite and food intake, elevated levels of IL-18 in obesity might suggest a compensatory mechanism." (PMID 39275140, 2024).
Obesity (continued). "Other studies evaluated IL-18 levels in patients with obesity before and after losing weight." (PMID 39275140, 2024). "Both clinical and experimental studies have demonstrated that adipose tissue macrophages (ATMs) secrete pro-inflammatory cytokines, including interleukin-1β (IL-1β) and IL-18, which are essential factors in the progression of obesity-related metabolic disorders." (PMID 39351493, 2024). "Because IL-18 has increased expression in obesity and HF and contributes to heart rhythm disorders and VT in mice, we suspect that IL-18 may heighten the IL-6 effects on ion channel function, pro-arrhythmic AP phenotypes, and ventricular arrhythmia risks." (PMID 39125976, 2024). "Four CVRPs were positively associated with obesity irrespective of age, leptin, IL-1Ra, IL-18 Ra, and MIP-1a, and all four were upregulated in PCOS." (PMID 39858399, 2024). "Future studies should examine IL-18 inhibitors and antagonists in obesity treatment." (PMID 39275140, 2024). "The highest levels of IL-18 were measured in patients with diabetes and obesity." (PMID 39275140, 2024). "The role of IL-18 (also produced upon inflammasome activation) in obesity, remains controversial." (PMID 37819510, 2023). "Moreover, the cytokines IL-18 and HGF showed strong positive associations with overweight and obesity." (PMID 37659013, 2023). "Moreover, ILC1s are crucial in obesity-related inflammation, secreting TNF-α, INF-γ and the costimulatory cytokine IL-18; the hallmark of ILC1 is the production of INF-γ because the subset of ILC1 127+ produces only INF-γ." (PMID 37189844, 2023). "We identified that elderly patients with obesity and/or diabetes mellitus were more susceptible to developing pneumonia and respiratory distress syndrome after SARS-CoV-2 infection, while the IL18-rs1834481 polymorphism was an independent risk factor for developing pneumonia." (PMID 37766191, 2023). "Moreover, it has been found that patients with obesity or type 2 diabetes mellitus are characterized by a IL-18 resistance after stimulation." (PMID 37659013, 2023). "People with obesity symptoms have IL-18 more in their serum concentration." (PMID 36677054, 2023). "Target of IL18 axis activity may become an attractive therapeutic strategy for obesity and diabetes." (PMID 36482059, 2022). "Obesity-related upregulation of IL-18, which experimentally limits food intake and food efficiency while promoting energy expenditure and fat oxidation could appear surprising." (PMID 36313762, 2022). "As a potent pro-inflammatory cytokine, elevated IL-18 levels were already observed in many low-grade inflammatory conditions such as obesity, metabolic syndrome, prediabetes, type 2 diabetes, latent autoimmune diabetes of the adults (LADA), hypertension, and dyslipidemia." (PMID 35263047, 2022). "Several studies highlighted the importance of IL18 in regulating obesity and energy homeostasis." (PMID 36482059, 2022). "It is known that IL18R and IL18 expression in adipose tissue is enhanced in nondiabetic obesity, and it is associated with a proinflammatory gene signature and insulin resistance in such patients." (PMID 35207726, 2022). "T2D, obesity, and stress can promote the release of IL-18 from microglia." (PMID 36186138, 2022). "In summary, it was demonstrated that obesity-related inflammation induced by high-fat diet could elevate serum IL-18 levels and exacerbate VC in CRF rats." (PMID 34901204, 2021). "The key findings of the current study were the significant interaction result of CETP rs708272 polymorphism with DIL and DII on obesity indices (WC and BMI), lipid profiles (TG, HDL, LDL/HDL), inflammatory markers (IL-18, CRP, and PGF2α), and antioxidant markers (TAC and SOD) in T2DM patients." (PMID 34354158, 2021). "Moreover, it was found that the levels of IL-18 were higher in patients with body mass index ≥30, suggesting a link between inflammasomes that activate IL-18 after viral infection and obesity." (PMID 33669011, 2021).
Obesity (continued). "However, a more recent work showed that IL-18 knockout mice develop spontaneous obesity due to lipid accumulation." (PMID 33806797, 2021). "In addition, studies have also shown that IL-18 is closely related to obesity and is one of the important regulators of obesity-related inflammation." (PMID 34901204, 2021). "Interestingly, secretion of IL-18 and IL-10, cytokines reported to negatively regulate high fat diet-induced obesity and insulin resistance, and protect against hepatic steatosis, respectively, were increased in our HFHC-fed HIL mice." (PMID 33013934, 2020). "IL18 is released by AT and its circulating levels increase in obesity and T2D." (PMID 32785109, 2020). "First, IL-18 is usually found in the circulation of individuals with obesity." (PMID 32906847, 2020). "Thus, NLRP1 appears to play a role in preventing obesity and metabolic syndrome in mice via the production of IL‐18." (PMID 32558991, 2020). "Indeed, reduced systemic levels of IL-18 when EPA is added to the diet of subjects with obesity has been reported." (PMID 32906847, 2020). "IL18 accelerates maturation of other immune cells, including T- and NK-cells, and enhances the production of other pro-inflammatory cytokines that exacerbate systemic inflammation in obesity and insulin resistance." (PMID 32785109, 2020). "Indeed, two recent studies have found that IL-33 and IL-18, which suppress obesity and metabolic dysfunction, can in fact act to limit A. muciniphila abundance in mice under certain settings." (PMID 31488830, 2019). "Evidence revealed that IL-18 is related to obesity, insulin resistance, and dyslipidemia." (PMID 31835423, 2019). "Although human adipocytes express IL-18, they are unlikely to contribute significant amounts of IL-18 into circulation and their increased levels associated with obesity." (PMID 30619282, 2018). "As in the case of IL6, elevated circulating IL18 serum levels were found in obese and T2DM patients, reduced after weight loss and were postulated as risk predictors for metabolic syndrome development before detection of obesity and IR." (PMID 30158466, 2018). "Increased levels of IL-18 and TNF-α have been described in the colon of diet-induced obese mice in parallel with alterations in the Wnt signaling pathway suggesting a mechanism for obesity-associated CC development." (PMID 30619282, 2018). "While the changes in IL‐18 are known, IL‐18R expression and relationship with IL‐18 and other inflammatory markers in the adipose tissue in obesity/type‐2 diabetes (T2D) remain unclear." (PMID 28508444, 2017). "Since we were unable to observe circulating IL-18 in IL-18BPKO mice, we reasoned that IL-18BPKO mice may be prone to obesity." (PMID 28900426, 2017). "We speculate that the increased IL‐18R/IL‐18 expression in the adipose tissue in obesity/T2D may play a role to induce or augment the inflammatory responses." (PMID 28508444, 2017). "In addition, some investigators correlated high levels of IL-18 and insulin resistance in patients with T2D, obesity or metabolic syndrome." (PMID 28950870, 2017). "Next, we wanted to know whether IL‐18R/IL‐18 expression changes in obesity were shown mainly by adipocytes or immune cells." (PMID 28508444, 2017). "The absence of IL-18 has been associated with obesity in mice that is observable between 20 and 24 weeks of age." (PMID 28900426, 2017). "We further asked whether the adipose tissue IL‐18R/IL‐18 mRNA expression in obesity and/or T2D was concordant with a local inflammatory state and insulin resistance in these individuals." (PMID 28508444, 2017). "However, the question remains that which immunometabolic factor(s) play a role in the induction or upregulation of IL‐18R and IL‐18 in the adipose tissue in obesity and/or T2D." (PMID 28508444, 2017).